NR2F6 (nuclear receptor subfamily 2 group F member 6)
Description:
Transcription factor predominantly involved in transcriptional repression. Binds to promoter/enhancer response elements that contain the imperfect 5'-AGGTCA-3' direct or inverted repeats with various spacings which are also recognized by other nuclear hormone receptors. Involved in modulation of hormonal responses. Represses transcriptional activity of the lutropin-choriogonadotropic hormone receptor/LHCGR gene, the renin/REN gene and the oxytocin-neurophysin/OXT gene. Represses the triiodothyronine-dependent and -independent transcriptional activity of the thyroid hormone receptor gene in a cell type-specific manner. The corepressing function towards thyroid hormone receptor beta/THRB involves at least in part the inhibition of THRB binding to triiodothyronine response elements (TREs) by NR2F6. Inhibits NFATC transcription factor DNA binding and subsequently its transcriptional activity. Acts as transcriptional repressor of IL-17 expression in Th-17 differentiated CD4(+) T cells and may be involved in induction and/or maintenance of peripheral immunological tolerance and autoimmunity. Involved in development of forebrain circadian clock; is required early in the development of the locus coeruleus (LC).
Synonyms: EAR-2; EAR2; ERBAL2
Tractability: Small molecule: it belongs to a druggable protein family. PROTAC: ubiquitination databases record sites on it.
Target class: Nuclear hormone receptor subfamily 2; Nuclear hormone receptor subfamily 2 group F member 6; Nuclear hormone receptor subfamily 2 group F; Nuclear receptor; Transcription factor
Gene: Protein-coding gene on chromosome 19 (17,231,883 to 17,245,919, reverse strand). Ensembl gene ENSG00000160113.
Subcellular location: Nucleus
Subcellular location (Human Protein Atlas): Nuclear speckles; Cytosol
Pathways (Reactome):
Gene expression (Transcription): Nuclear Receptor transcription pathway
Gene Ontology:
Molecular function: DNA-binding transcription factor activity; protein binding; sequence-specific DNA binding; sequence-specific double-stranded DNA binding; DNA-binding transcription factor activity, RNA polymerase II-specific; nuclear receptor activity; RNA polymerase II cis-regulatory region sequence-specific DNA binding; DNA-binding transcription repressor activity, RNA polymerase II-specific; zinc ion binding
Biological process: negative regulation of transcription by RNA polymerase II; cell differentiation; nervous system development; intracellular receptor signaling pathway; regulation of DNA-templated transcription
Cellular component: mitochondrion; nuclear speck; nucleus; chromatin; nucleoplasm
Genetic constraint (gnomAD): Loss-of-function variants: 20 observed, 23.14 expected, observed/expected ratio (o/e) 0.86, 90% interval 0.61 to 1.26. The synonymous counts are far from expectation, so gnomAD's model fits this gene poorly and the ratio says little. Missense variants: 536 observed, 477.58 expected, observed/expected ratio (o/e) 1.12, 90% interval 1.04 to 1.21. Synonymous variants: 325 observed, 241.59 expected, observed/expected ratio (o/e) 1.35, 90% interval 1.23 to 1.48.
Homologues: Orthologues: dog NR2F6 (99% identical), macaque NR2F6 (99% identical), pig NR2F6 (99% identical), chimpanzee NR2F6 (97% identical), guinea pig NR2F6 (93% identical), rat Nr2f6 (92% identical), mouse Nr2f6 (92% identical), tropical clawed frog nr2f6 (80% identical), zebrafish nr2f6a (75% identical), zebrafish nr2f6b (74% identical), Caenorhabditis elegans nhr-41 (33% identical), Drosophila melanogaster Hr78 (30% identical), and 25 more. Paralogues in human: NR2F1 (63% identical), NR2F2 (63% identical), RXRA (39% identical), RXRG (38% identical), RXRB (37% identical), NR2E3 (37% identical), NR2C2 (35% identical), HNF4A (34% identical), HNF4G (34% identical), NR2E1 (33% identical), NR2C1 (33% identical).
Diseases named in the same sentence as NR2F6 in open-access papers:
NR2F6 is named in the same sentence as 81 diseases in open-access papers, as found by Europe PMC text mining. Sharing a sentence is not in itself a finding about the gene and the disease. The quoted sentences say what the papers report.
hepatocellular carcinoma (17 papers, 2019 to 2025). A malignant tumor that arises from hepatocytes. "Additionally, NR2F6 has been associated with colorectal cancer progression and hepatocellular carcinoma cell proliferation and metastasis." (PMID 40424451, 2025). "For instance, circRHOT1 inhibited the progression of hepatocellular Carcinoma (HCC) via recruiting TIP60 to the NR2F6 promoter and subsequently initiating the transcription of NR2F6." (PMID 37296107, 2023). "Knockdown of circRHOT1 inhibits the transcription of NR2F6, and also inhibits the proliferation and metastasis of hepatoma cells." (PMID 36966306, 2023). "CircRHOT1 is highly expressed in hepatocellular carcinoma and regulates cell proliferation, cell migration, cell invasion, and inhibits apoptosis by modulating NR2F6 transcription." (PMID 34449657, 2021). "It has been reported that circRHOT1 enhances the progression of hepatocellular carcinoma by inducing NR2F6 expression." (PMID 34406978, 2021). "Recruitment of TIP60 promotes histone acetylation of the NR2F6 promoter leading to upregulation of NR2F6 transcription in hepatocellular carcinoma and correlates with poor prognosis." (PMID 34449657, 2021). "Human studies firmly established an increased NR2F6 expression in various cancer types such as leukemia, colon carcinoma, cervical cancer, ovarian cancer, breast cancer, lung cancer and hepatocellular cancer, suggesting that NR2F6 might be a prognostic marker." (PMID 34073258, 2021). "Besides its role in immune cells, NR2F6 is upregulated in various human cancer cells, such as cervical cancer, ovarian cancer, colon carcinoma, leukemia, lung cancer, breast cancer, and hepatocellular cancer, indicating that NR2F6 is involved in tumor promotion and progression." (PMID 37575237, 2023). "CircRHOT1 was found to promote hepatocellular carcinoma (HCC) growth through the recruitment of TIP60 to the promoter of NR2F6 and initiating NR2F6 transcription." (PMID 33516252, 2021). "CircRHOT1 expression accelerates hepatocellular carcinoma (HCC) growth and metastasis by initiating NR2F6 transcription." (PMID 37993909, 2023). "For example, circRHOT1 promotes hepatocellular carcinoma (HCC) growth and metastasis by recruiting TIP60 to the NR2F6 promoter." (PMID 35780119, 2022). "For hepatocellular carcinoma (HCC), the transcription of NR2F6 could be activated by circRHOT1 and therefore promote the progression of patients with HCC." (PMID 34304715, 2021). "circRHOT1 recruits Tat-interactive protein 60 kDa (TIP60) to the nuclear receptor subfamily 2 group F member 6 (NR2F6) promoter, thereby promoting cell proliferation, migration, and invasion in hepatocellular carcinoma through the induction of proto-oncogene expression." (PMID 36713460, 2022). "In hepatocellular carcinoma (HCC), upregulated circRHOT1 recruits TIP60 to the promoter of NR2F6, initiating NR2F6 transcription and promoting HCC development and progression." (PMID 39901896, 2025). "CircRHOT1 was highly expressed in advanced hepatocellular carcinoma (HCC) tissues and inhibited HCC progression by recruiting TIP60 to initiate NR2F6 transcription." (PMID 38544689, 2024). "High expression of circRHOT1 in hepatocellular carcinoma (HCC) significantly promotes the growth and metastasis of HCC, with circRHOT1 recruiting TIP60 to the NR2F6 promoter, initiating NR2F6 transcription." (PMID 36966306, 2023).
breast carcinoma (12 papers, 2015 to 2025). "Overall, NR2F6 has been proven to be closely associated with the progression of multiple malignant tumors, such as cervical cancer, colon cancer, and breast cancer." (PMID 36119482, 2022). "In brief, the results indicate that the breast cancer risk SNP rs4808611 promotes the gene expression of NR2F6 and then results in a poor prognosis for breast cancer patients." (PMID 34889888, 2021). "For the functional site rs4808611, the risk allele C upregulates the NR2F6 gene and contributes to a poor prognosis for breast cancer patients." (PMID 34889888, 2021). "The Kaplan–Meier analysis showed that the higher expression of the NR2F6 gene was associated with poor relapse-free survival for breast cancer patients." (PMID 34889888, 2021). "The rs4808611 site in 19p13.11 loci, one intron variant in the NR2F6 gene, has been associated with breast cancer risk." (PMID 34889888, 2021). "In our analysis on gene NR2F6, we found that the higher expression of NR2F6 was significantly associated with the lower survival probability for breast cancer patients." (PMID 34889888, 2021). "In the gene regulatory network by using the NetworkAnalyst web server, we found five (two from Encode and three from Jasper such as FOXC1, GATA2, FOXL1, ZNF24 and NR2F6) potential Transcription Factors (TFs) and all of those are linked with several cancer including breast cancer." (PMID 38717954, 2024). "We found that the C allele of rs4808611 may affect the risk progression of breast cancer by promoting the expression of NR2F6 (HGNC:7977)." (PMID 34889888, 2021). "Previous studies have also shown increased NR2F6 expression in leukemia patients, breast cancer with poor prognosis, cervical cancer with pelvic lymph node metastasis and poor prognosis, and chemotherapy-resistant ovarian cancer." (PMID 40424451, 2025). "Functional investigations show that rs4808611 affects breast cancer progression by altering the gene expression of NR2F6." (PMID 34889888, 2021). "Although NR2F6 was identified to be the hub genes involved in the pathogenesis and progression of breast cancer, the regulatory mechanisms in breast cancer are unclear." (PMID 34889888, 2021). "Similar to our inquiry in breast cancer, NR2F6 has already been proven upregulated frequently in bladder cancer tissues compared with their paired normal tissues." (PMID 34889888, 2021). "Relative to the normal gland, NR2F6 is over-expressed in all PAM50-classified breast-cancer sub-types." (PMID 26894976, 2016). "Lower expression of Hepatocyte Nuclear Factor 4 alpha (HNFα, NR2A1) and higher expression of V-erbA related protein (EAR2, NR2F6) were associated with increased DFS in patients with the Luminal A subtype of breast cancer (p = 0.035 and p = 0.038, respectively)." (PMID 26300846, 2015). "The expression of NR2F6 is significantly up-regulated in a variety of malignant tumors, such as acute myeloid leukemia (AML), breast cancer, Head and neck squamous cell carcinoma, colon cancer, and lymphoma." (PMID 36119482, 2022). "However, given over-expression in all breast-cancer sub-types, NR2F6 may be a pro-oncogene." (PMID 26894976, 2016). "NR2F6 is more highly expressed in breast cancer than in normal breast tissue; NR profiling with the NCI-60 cancer cell panel indicates that cells with lower NR2F6 expression exhibit higher sensitivity to anti-cancer drugs targeting microtubules." (PMID 27775588, 2016). "Nuclear receptor subfamily 2 group F member 6 (NR2F6) could transcriptionally activate ACAT1 and enhance the suppressive role of ACAT1-induced METTL3 acetylation on cell migration and invasion of breast cancer." (PMID 38720812, 2024). "Moreover, NR2F6 is overexpressed in a variety of malignancies, including lymphoma, head and neck squamous cell carcinoma, acute myeloid leukemia (AML), colon cancer, and breast cancer." (PMID 37575237, 2023). "There are no studies on the significance of NR2F6 in mammary-tumors." (PMID 26894976, 2016).
colon carcinoma (11 papers, 2016 to 2025). "NR2F6 knockdown by RNA interference (RNAi) induces colon cancer cell apoptosis by inhibiting the X-linked inhibitor of apoptosis protein (XIAP) expression." (PMID 27775588, 2016). "The mutational landscape suggested that NR2F6 could be observed as a distinct gene mutation in cancers such as colon cancer (COAD) and gastric adenocarcinoma (STAD)." (PMID 40424451, 2025). "As noted, it was previously reported that NR2F6 global KO mice harboring mouse melanoma and colon cancer models showed enhanced responses to programmed death-ligand 1/PD-1 ICT relative to comparable WT mice." (PMID 37406115, 2023). "Along this line of argumentation, a positive correlation between NR2F6 expression and cancer has been reported; studies have identified NR2F6 to be upregulated in human ovarian cancer, colon cancer and lymphoma." (PMID 29670099, 2018). "NR2F6 was also defined as an intracellular immune checkpoint in tumor-infiltrating T cells and is significantly related to the survival outcomes of numerous cancers, such as head and neck squamous cell carcinoma, early-stage cervical cancer, and colon cancer." (PMID 33456631, 2020). "Furthermore, without fully understanding the complete function of NR2F6 in HNSCC cells, the expression of NR2F6 within cancer cells instead of immune cells has been shown before in other solid cancer types (e.g., colon cancers)." (PMID 32752295, 2020). "NR2F6 overexpression is related to tumor aggressiveness in leukemia and colon cancer." (PMID 27775588, 2016). "We expected that the transcription factors WRNIP1, ATF1, CBFB, and NR2F6, as well as the microRNAs miR-1-3p, miR-26b-5p, miR-164a-5p, and miR-9-5p, would play essential roles in metabolic abnormalities of cells in obese people and the development of colon cancer." (PMID 37711894, 2023). "However, NR2F6 has not only been described in tumor-infiltrating lymphocytes, but also in tumor cells of different solid cancer types, e.g., hepatocellular carcinoma, ovarian cancer, cervical cancer, and colon cancer." (PMID 32752295, 2020). "Challenging Nr2f6+/+ and Nr2f6−/− mice with a high tumor load of 5×105 B16-OVA or 7.5×105 MC38 colon carcinoma cells, all wild-type mice receiving control IgG injections rapidly developed tumors and had to be sacrificed due to ethical reasons at the latest by d21 post injection." (PMID 29670099, 2018).
ovarian carcinoma (11 papers, 2018 to 2025). A malignant neoplasm originating from the surface ovarian epithelium. "Previous studies have found that the high expression level of NR2F6 is associated with poor prognosis in various malignant tumors, such as ovarian cancer, early cervical cancer, and head and neck cancer." (PMID 36119482, 2022). "In ovarian cancer, Nr2f6 promotes cell proliferation by tethering the histone acetylase P300 to the Notch3 promoter." (PMID 38682559, 2024). "Many studies also established increased expression of NR2F6 in various cancer types including ovarian cancer, describing correlations between increased expression, faster tumour growth, and worse patient outcome." (PMID 37370765, 2023). "This was consistent with previously reported results, overexpression of NR2F6 predicted poor patient prognosis in various malignant tumors, such as ovarian cancer, early cervical cancer, and head and neck cancer." (PMID 37575237, 2023). "Recent reports showed that NR2F6 is involved in human cancers such as ovarian cancer and cervical cancer." (PMID 31324186, 2019). "Furthermore, NR2F6 expression has been identified to confer cisplatin resistance in epithelial ovarian cancer cells." (PMID 39341888, 2024). "Moreover, NR2F6 overexpression has previously been described to promote the chemoresistance of epithelial ovarian cancer via activation of Notch3." (PMID 37370765, 2023). "Liu’s study indicated that NR2F6 overexpression was related to poor overall survival and also stimulated DDA1 transcription by binding to the promoter region in ovarian cancer." (PMID 34304715, 2021).
cervical cancer (9 papers, 2016 to 2025). A primary or metastatic malignant neoplasm involving the cervix. "Therefore, we assessed whether NR2F6 upregulation is clinically associated with cervical cancer development and progression." (PMID 27775588, 2016). "This is the first study to evaluate NR2F6 expression and its clinical significance in early-stage cervical cancer." (PMID 27775588, 2016). "Multivariate Cox regression analysis determined that NR2F6 protein level and recurrence were independent prognostic markers for early-stage cervical cancer." (PMID 27775588, 2016). "In the present study, NR2F6 mRNA and protein were upregulated in cervical cancer cell lines and cervical cancer tissue (stage IB–IIA)." (PMID 27775588, 2016). "Univariate and multivariate analysis determined that NR2F6 was an independent prognostic factor of survival in early-stage cervical cancer." (PMID 27775588, 2016). "The relevance between NR2F6 expression and early-stage cervical cancer prognosis and clinicopathological features was determined." (PMID 27775588, 2016). "Herein, we explored the NR2F6 expression characteristics in cervical cancer cell lines and early-stage cervical cancer tissues." (PMID 27775588, 2016). "Overall and disease-free survival was shorter in patients with early-stage cervical cancer and higher NR2F6 levels than in patients with lower levels of NR2F6." (PMID 27775588, 2016). "We also investigated the relationship between NR2F6 protein expression and the clinical manifestations and survival outcome of 189 early-stage cervical cancer cases." (PMID 27775588, 2016). "NR2F6 mRNA and protein expression were overexpressed in all cervical cancer cell lines as compared to the Ect1/E6E7 cell line, indicating that NR2F6 is upregulated in cervical cancer cell lines." (PMID 27775588, 2016). "We explored NR2F6 expression and its clinicopathological significance in early-stage cervical cancer." (PMID 27775588, 2016). "The abnormal high expression of NR2F6 in early-stage cervical cancer predicts pelvic lymph node metastasis, tumor recurrence and poor prognosis and NR2F6 might be a potential therapeutic target of cervical cancer." (PMID 30967126, 2019). "NR2F6 expression in 189 human early-stage cervical cancer tissue samples was evaluated using IHC." (PMID 27775588, 2016). "Univariate and multivariate analyses revealed that NR2F6 expression might be an independent prognostic predictor of poor prognosis in early-stage cervical cancer." (PMID 27775588, 2016). "Multivariate analysis suggested that NR2F6 expression might be an independent prognostic marker of survival in early-stage cervical cancer." (PMID 27775588, 2016). "Our findings showed that NR2F6 may be a promising prognostic indicator for early-stage cervical cancer." (PMID 27775588, 2016). "NR2F6 might be a useful prognostic biomarker and potential therapeutic target for early-stage cervical cancer." (PMID 27775588, 2016). "Taken together, our findings suggest that NR2F6 may be a promising novel biomarker and therapeutic target for treating early-stage cervical cancer." (PMID 27775588, 2016). "Therefore, our results demonstrate that NR2F6 expression may be a more significant predictor of the prognosis for patients with early-stage cervical cancer who require chemotherapy." (PMID 27775588, 2016). "NR2F6 might be a novel prognostic biomarker and potential therapeutic target of cervical cancer." (PMID 27775588, 2016). "However, NR2F6 expression characteristics and its clinical significance in cervical cancer remain unknown." (PMID 27775588, 2016). "Therefore, we hypothesize that NR2F6 might be a therapeutic target in early-stage cervical cancer." (PMID 27775588, 2016). "We demonstrate that NR2F6 is upregulated in cervical cancer, and is correlated with PLNM, tumor recurrence, and poor prognosis in early-stage cervical cancer." (PMID 27775588, 2016). "In HeLa-S3, the cervical carcinoma cell line (E117), PROX1 and NR2F6 were found by DeepHistone." (PMID 30967126, 2019).